PIM1 (Pim-1 proto-oncogene, serine/threonine kinase)
Diseases named in the same sentence as PIM1 in open-access papers (continued):
Sharing a sentence is not in itself a finding about the gene and the disease.
diffuse large B-cell lymphoma (19 papers, 2014 to 2025). "Specifically, PIM-1 overexpression has been observed in diffuse large B-cell lymphoma (DLBCL), acute myeloid leukemia (AML), and chronic lymphocytic leukemia (CLL), correlating with advanced disease stages and reduced survival rates." (PMID 39434908, 2024). "The result showed 23 gene mutations, including MYD88, CD79B, CDKN2A, PIM1, RELN, PCLO, CREBBP, and so on, supporting the diagnosis of diffuse large B-cell lymphoma." (PMID 36599976, 2023). "The genetic test results of the left frontal parietal lobe lesion result revealed 23 gene mutations, including MYD88, CD79B, CDKN2A, PIM1, RELN, PCLO, CREBBP, and so on, supporting the diagnosis of diffuse large B-cell lymphoma." (PMID 36599976, 2023). "Mutations in CREBBP, TNFRSF14 and KMT2D predominated in follicular lymphoma, whereas those in BTG2, HTA-A and PIM1 were more frequent in diffuse large B-cell lymphoma." (PMID 33945543, 2021). "LncRNA SNHG16 sponges miR-497-5p and elevates PIM1 expression, boosting cell proliferation and suppressing apoptosis in diffuse large B-cell lymphoma cells." (PMID 32297639, 2020). "In patients with a clinically normal immune function, the Epstein-Barr virus is predominantly negative, and the mutation frequency of proto-oncogenes, including Pim-1, RhoH/TTF and c-Myc, is two to five-fold higher than in patients with extracranial diffuse large B-cell lymphomas." (PMID 25789045, 2015). "Pim-1 overexpression has been associated with upregulated cell surface expression of CXCR4 in hematopoietic malignancies such as acute myeloid leukemia, diffuse large B-cell lymphoma and chronic lymphocytic leukemia." (PMID 26075720, 2015). "Expression of both PIM1 and PIM2 are elevated in diffuse large B-cell lymphoma (DLBCL), while PIM2 alone is most highly expressed in B-cell chronic lymphocytic leukemia, acute myeloid leukemia (AML), and MM." (PMID 34503111, 2021). "For example, expression of both PIM1 and PIM2 is elevated in diffuse large B-cell lymphoma (DLBCL), whereas PIM2 alone is more highly expressed in B-cell chronic lymphocytic leukemia, acute myeloid leukemia (AML), and multiple myeloma (MM)." (PMID 29927999, 2018).
acute myeloid leukemia (18 papers, 2012 to 2025). Acute myeloid leukemia (AML) is a group of neoplasms arising from precursor cells committed to the myeloid cell-line differentiation. "In acute myeloid leukemia (AML) increased levels of Pim-1 have been associated with aberrant expression of the mixed-line-age leukemia (MLL) gene as a consequent activation of tyrosine-kinase receptor FLT3 or the transcriptional regulator Hoxa9." (PMID 25491234, 2014). "Conversely, PIM1 was found to be enriched in several pathways including microRNAs in cancer and acute myeloid leukemia." (PMID 40649898, 2025). "The main purpose of this study were to investigate that the correlation between PIM-1 mRNA levels and clinicopathologic features and its clinical significance in acute myeloid leukemia (AML)." (PMID 28851457, 2017). "For instance, PIM1 overexpression in a number of hematopoietic cancers could promote the clinical investigation of rucaparib in acute myeloid leukemia." (PMID 24632590, 2014). "PIM-1 is overexpressed in various hematopoietic malignancies, such as multiple myeloma, mantle cell lymphoma and diffuse large B-cell lymphomas, as well as in FLT 3/ITD positive acute myeloid leukemia (AML)." (PMID 23115625, 2012). "In acute myeloid leukemia (AML), a link has been found between PIM1 kinase activity and the surface expression and function of the CXCR4 receptor, with PIM1 expression levels correlating with CXCR4 surface expression." (PMID 29666622, 2018).
lung carcinoma (13 papers, 2011 to 2024). "In tumor models of lung carcinoma or pancreatic carcinoma, PIM-1 expression has been associated with a decrease in radiosensitivity." (PMID 34993612, 2022). "Studies in experimental models of lung carcinoma or pancreatic carcinoma have shown that PIM-1 expression is associated with a reduction in radiosensitivity." (PMID 34993612, 2022). "Therefore, upregualtion of Pim-1 was associated with aggressive behaviour of lung cancer." (PMID 25342548, 2014). "Several previous studies demonstrated a strong link between increased PIM1 expression and drug resistance, invasion, and metastasis in lung cancer." (PMID 39227379, 2024). "Second, our experimental validation on drug combination of BRAF inhibitor and PIM1 inhibitor was evaluated using two lung cancer cell lines." (PMID 26916442, 2016). "One of our predicted biomarker pairs, a mutation in the BRAF gene and upregulated expression of the PIM1 gene, was experimentally validated to benefit from a therapy combining BRAF inhibitor and PIM1 inhibitor in lung cancer." (PMID 26916442, 2016). "Other studies have reported that a high PIM-1 level correlates with good prognosis in prostate adenocarcinoma, pancreatic ductal carcinoma, and nonsmall cell lung cancer." (PMID 25040935, 2014). "Reportedly, OPN acts through αvβ3 integrin, which in turn activates the FAK, PI3K, Akt, ERK, NF-κB and Pim-1 pathways, thus contributing to the migration of lung cancer cells." (PMID 23119061, 2012). "Therefore, Pim-1 is a critical survival protein contributed to tumorgenesis and progression of lung cancer." (PMID 25342548, 2014). "Pim-1 regulates the proliferation, differentiation and apoptosis of lung cancer cells." (PMID 23119061, 2012). "In lung cancer, ectopic expression of miR-1 reduced the protein levels of MET, Pim-1, FoxP1, and HDAC4 to influence the survival of cancer cells and oncogenic properties." (PMID 28537886, 2017). "Concurrently, these results suggest that OPN mediates migration in human lung cancer cells via the αvβ3 integrin, FAK, PI3K, Akt, ERK, NF-κB and Pim-1 signaling pathways." (PMID 23119061, 2012). "It was reported that the treatment with HDAC as an inhibitor of lung cancer cells could induce the expression of repressed miR-1 by the downregulation of oncogenes such as MET, PIM1, FOXP1, and HDAC4." (PMID 37569812, 2023). "Reports indicate that miR-101-3p targets Pim-1 in salivary gland adenoid cystic carcinoma to enhance the sensitivity to chemotherapy and suppress cell proliferation and invasion; miR-101-3p was also reported to target MALAT-1 in nonsmall cell lung cancer to inhibit growth and metastasis." (PMID 32411089, 2020).
pancreatic cancer (13 papers, 2012 to 2024). "In the current study, we measured plasma PIM-1 levels and then assessed their diagnostic value in pancreatic cancer." (PMID 27596051, 2016). "Our study suggests that PIM-1 contributes to malignancy and has diagnostic and prognostic value in pancreatic cancer." (PMID 27596051, 2016). "Plasma PIM-1 levels displayed diagnostic values for distinguishing patients with pancreatic cancer from healthy volunteers, patients with chronic pancreatitis, and patients with other pancreatic tumours (P = 0.000, P = 0.000, and P = 0.001, respectively)." (PMID 27596051, 2016). "Plasma PIM-1 levels also displayed potential diagnostic value in pancreatic cancer." (PMID 27596051, 2016). "PIM1 is upregulated in primary pancreatic tumor tissue compared to matched normal tissue in PDAC patients due to hypoxic environment and has been identified as prognostic marker." (PMID 37943821, 2023). "PIM1 has been demonstrated to be overexpressed and a potential biomarker in serval types of cancers, such as pancreatic cancer, colorectal cancer and acute myeloid leukemia." (PMID 30989585, 2019). "PIM1 has been shown to play a role in hypoxia-induced cisplatin resistance in pancreatic cancer cells, and a kinase dead form of PIM1 was sufficient to resensitize the cells to cisplatin, even in hypoxia." (PMID 28383481, 2017). "When patients with pancreatic cancer were distinguished from healthy volunteers, plasma PIM-1 levels were significantly superior to CA19-9 levels (0.984 vs. 0.897, respectively; P = 0.0019), particularly in terms of sensitivity (95.6 vs. 74.4 %)." (PMID 27596051, 2016). "We also found that PIM-1 expression in pancreatic cancer tissues was significantly upregulated and that a high level of expression was negatively associated with prognosis (P = 0.025, hazard ratio [HR] =2.113, 95 % confidence interval: 1.046–4.266)." (PMID 27596051, 2016). "Univariate analysis indicated that TNM staging and PIM-1 expression level were potential prognostic factors for pancreatic cancer." (PMID 27596051, 2016). "Knockdown of PIM-1 expression in pancreatic cancer cells suppressed proliferation, induced cell cycle arrest, enhanced apoptosis, resensitized cells to gemcitabine and erlotinib treatment, and inhibited ABCG2 and EZH2 mRNA expression." (PMID 27596051, 2016). "Conversely, Pim-1 and IL-6 mRNA and protein levels were increased in pancreatic cancer tissues as compared to normal tissues in four randomly selected paired samples." (PMID 26894969, 2016). "In the present study, we demonstrated that the PIM-1 expression level in tissue was an independent poor prognostic factor, which is consistent with the oncogenic role of PIM-1 in pancreatic cancer." (PMID 27596051, 2016). "Pim-1 also enhances NFATc1 activity, which increases proliferation and anchorage-independent growth in pancreatic cancer." (PMID 26894969, 2016). "Eighty-two patients with pancreatic cancer with complete medical records and follow-up information were divided into high- and low-level expression groups according to median plasma PIM-1 levels." (PMID 27596051, 2016). "When patients with pancreatic cancer were distinguished from patients with chronic pancreatitis, plasma PIM-1 levels were also significantly superior to CA19-9 levels (0.895 vs. 0.785, respectively; P = 0.0178), but the specificity was lower (77.8 vs. 88.9 %)." (PMID 27596051, 2016). "High plasma PIM-1 expression was an independent adverse prognostic factor for pancreatic cancer (P = 0.037, HR = 1.87, 95 % CI: 1.04–3.35)." (PMID 27596051, 2016). "The current study aimed to investigate the roles of PIM-1 in regulating biological behaviours of pancreatic cancer, including proliferation, apoptosis, the cell cycle, gemcitabine and erlotinib sensitivity, and cancer stem cells." (PMID 27596051, 2016). "Twenty-four of 90 pancreatic cancer samples showed low-level PIM-1 protein expression, and 66 of 90 pancreatic cancer samples showed high-level PIM-1 protein expression." (PMID 27596051, 2016).
pancreatic cancer (continued). "PIM-1 is involved in regulating cell proliferation, the cell cycle, apoptosis and chemoresistance in multiple tumours, including pancreatic cancer." (PMID 27596051, 2016). "First, the pancreatic cancer tissues analysed in the study were obtained from surgical resection, so there was inherent bias to analyse the relativity between PIM-1 expression levels and TNM stages because few patients were eligible for surgical resection." (PMID 27596051, 2016). "We found that PIM-1 knockdown in pancreatic cancer cells suppressed proliferation, induced cell cycle arrest, enhanced apoptosis, resensitized cells to gemcitabine and erlotinib treatment, and inhibited ABCG2 and EZH2 mRNA expression." (PMID 27596051, 2016). "The roles and mechanisms by which PIM-1 levels increase in pancreatic cancer stroma should be demonstrated in future studies." (PMID 27596051, 2016). "PIM1 was induced by hypoxia in pancreatic cancer cell lines, in which PIM1 is stabilized by hypoxia by preventing it from ubiquitin-mediated proteasomal degradation." (PMID 25834102, 2015). "For instance, blocking PIM1 function via the introduction of a dominant-negative PIM1 sensitizes pancreatic cancer cells to apoptosis induced by glucose deprivation." (PMID 25749522, 2015). "TTP over-expression influenced the expression of several tumor-related factors, and our results suggest that TTP may reduce pancreatic cancer cell proliferation and increase patient survival through downregulation of Pim-1 and IL-6." (PMID 26894969, 2016). "However, Reiser-Erkan and colleagues showed that the presence of PIM-1 in pancreatic cancer cells had a favourable prognostic impact." (PMID 27596051, 2016). "We also investigated the mechanisms by which PIM-1 regulates pancreatic cancer progression." (PMID 27596051, 2016). "PIM-1 is upregulated in pancreatic cancer tissues and plasma and may serve as an independent adverse prognostic factor for pancreatic cancer." (PMID 27596051, 2016). "We also found that a high plasma PIM-1 level was an independent adverse prognostic factor and could serve as a new prognostic marker for pancreatic cancer." (PMID 27596051, 2016). "The role of PIM-1 in pancreatic cancer has been investigated." (PMID 27596051, 2016). "Given the already-reported roles of Pim-1 and IL-6 in pancreatic cancer tumorigenesis, we speculate that TTP may reduce cancer cell proliferation though downregulation of Pim-1 and IL-6." (PMID 26894969, 2016). "The effects of PIM-1 on the progression of pancreatic cancer remain unclear, and the prognostic value of PIM-1 levels in tissues is controversial." (PMID 27596051, 2016). "In addition, plasma levels of PIM-1 in patients with pancreatic cancer were significantly higher than were those in all control subjects combined (29.8 ± 47.7 ng/ml vs. 7.21 ± 8.3 ng/ml, P = 0.000)." (PMID 27596051, 2016). "Downregulation of Pim-1, a member of the serine/threonine protein kinase family and an oncogene involved in cell survival, proliferation, differentiation and tumorigenesis, reduces tumorigenicity and increases apoptosis in pancreatic cancer cells." (PMID 26894969, 2016). "Therefore, it is possible that the increased levels of βIII-tubulin allow for PIM1 to exert its pro-survival effect in pancreatic cancer cells." (PMID 25544769, 2015). "In pancreatic cancer, PIM1 contributes to chemoresistance; hence, it is worthwhile to further explore whether PIM1 carries a similar function in HCC, a deadly cancer that is notorious for its chemoresistance." (PMID 25834102, 2015). "Furthermore, we previously showed that human pancreatic cancer cells express much lower levels of Pim-1 and Pim-2 mRNA than Pim-3 mRNA." (PMID 25971209, 2015). "Moreover, dominant-negative PIM1 reduces tumorigenicity in pancreatic cancer cells and HeLa xenograft mouse models." (PMID 25749522, 2015). "However, the regulatory roles and mechanisms of PIM-1 in pancreatic cancer are still unclear." (PMID 27596051, 2016).
pancreatic cancer (continued). "Thus, the combination of PIM-1 inhibitor with erlotinib may be new method for pancreatic cancer therapy in future investigations." (PMID 27596051, 2016). "Thus, the potential mechanism by which PIM-1 affects sensitivity to the chemotherapy drug erlotinib or the expression of pancreatic cancer stem cell markers in pancreatic cancer may be by regulating the EGFR signalling pathway." (PMID 27596051, 2016). "Additionally, we found that plasma PIM-1 levels in patients with pancreatic cancer were significantly increased and could be used in the diagnosis of pancreatic cancer." (PMID 27596051, 2016). "Our study is the first to verify the feedback loop between PIM-1 and the EGFR signalling pathway in pancreatic cancer." (PMID 27596051, 2016). "Therefore, the plasma PIM-1 level could be a new marker for TNM staging of pancreatic cancer." (PMID 27596051, 2016). "Thus, PIM-1 may be a biomarker and potential therapeutic target in pancreatic cancer." (PMID 27596051, 2016). "In conclusion, PIM-1 and the EGFR pathway form a feedback loop, which contributes to the malignancy of pancreatic cancer." (PMID 27596051, 2016). "PIM-1 levels in tissues and plasma were independent prognostic factors, and PIM-1 may be a new prognostic biomarker for pancreatic cancer." (PMID 27596051, 2016). "The feedback loop of PIM-1 and the EGFR signalling pathway would be strengthened if the relevance of expression levels between PIM-1 and EGFR could be verified in pancreatic cancer." (PMID 27596051, 2016). "The roles and mechanisms of increased levels of PIM-1 in stroma have not been elucidated in pancreatic cancer." (PMID 27596051, 2016). "We also investigated the expression levels of the pancreatic cancer stem cell markers ABCG2 and EZH2 by qRT-PCR, and we found that ABCG2 and EZH2 mRNA expression levels were significantly decreased following siRNA-mediated knockdown of PIM-1 expression." (PMID 27596051, 2016). "Plasma PIM-1 levels in patients with pancreatic cancer have not been described." (PMID 27596051, 2016).
B-cell lymphomas (12 papers, 2013 to 2025). "The prognostic significance of PIM1 mutation or expression observed in earlier B‐cell lymphoma studies is due to its association with ABC‐DLBCL,6, 18, 25 wherein PIM1 mutations are thought to stabilize its nuclear expression resulting in a gain‐of‐function." (PMID 39548807, 2025). "In contrast to other malignancies, mature B-cell lymphomas displayed a high rate (18.5%) of mutations, especially in Pim1." (PMID 36694243, 2023). "While Pim-1 and MYC transgenic mice were predisposed to T- and B cell lymphomas, respectively, double transgenic Eμ Pim-1 and Eμ MYC developed an aggressive pre-B leukemia in utero with death at or before birth." (PMID 26186558, 2015). "Whole genome sequencing finds that almost 8% of DLBCLs, CLL, MLL, mature B-cell lymphomas, and cutaneous T-cell lymphomas carry Pim-1 genetic alterations." (PMID 36694243, 2023). "Insertion of the Moloney-murine leukemia virus (M-MuLV), into either Pim gene locus leads to enhanced protein expression of Pim-1/− 2 that can lead to T- and B-cell lymphomas." (PMID 36694243, 2023). "In hematopoietic malignancies, B-cell lymphomas with up-regulated AID have been shown to carry adverse mutations in genes, such as MYC, PIM1, and PAX5, as well as chromosomal abnormalities, including MYC/IGH rearrangements." (PMID 30679751, 2019). "The pim-1 gene was originally discovered as a common insertion site in MoMuLV-induced T cell lymphomas and later found in B-cell lymphomas and erythroleukemias." (PMID 27287229, 2016). "In contrast, in B-cell lymphomas that are induced by M-MLuV or other lymphoid diseases induced by different viruses, the frequency of insertions at pim1 is greatly reduced." (PMID 24860787, 2014). "In 1997, it was shown that the eis-1/pal-1/gfi-1/evi-5 locus serves as a target for M-MuLV proviral insertions in pre-B-cell lymphomas in Eμ-myc transgenic mice (20%) and in T-cell lymphomas in H2K-myc (75%) and Eμ-pim1 (93%) transgenic mice." (PMID 24860787, 2014). "In Pim1-KO mice, integration of M-MulV into the pim2 locus, which occurs in 25% of all integrations, provokes T- and B-cell lymphoma via enhanced mRNA production." (PMID 24860787, 2014). "PIM1, in cooperation with Myc, promotes the development of pre-B-cell lymphoma in mice." (PMID 36429128, 2022). "Integrations into the pim1 locus (mouse chromosome 17, which corresponds to human 6p21) lead to increased mRNA production, increased levels of wild-type protein, and the development of T- and B-cell lymphomas." (PMID 24860787, 2014). "Most notably, Pim-1 can synergize with c-Myc to drive the rapid progression of B-cell lymphomas." (PMID 25121590, 2014). "The extent of the role of Pim1 in tumorigenicity seems to depend on the tissue affected and the nature of the molecular pathways activated by the co-expressing oncogenes; overexpression of cMyc and Pim1 in lymphoid tissues resulted in the death of mice in utero from pre-B cell lymphoma." (PMID 23565217, 2013). "SHA of the Pim-1 gene has also been shown for AIDS-related non-Hodgkin lymphomas (AIDS-NHLs) and HCV-positive B-cell NHL patients." (PMID 36694243, 2023). "However, the MYD88 L265P and PIM1 p.G28A, p.L184V, and p.V197F mutations have not yet been examined in conjunction with MYD88 and PIM1 protein expression in large B-cell NHL cases." (PMID 38335426, 2024).